SALL1 (spalt like transcription factor 1)
Diseases named in the same sentence as SALL1 in open-access papers (continued):
Sharing a sentence is not in itself a finding about the gene and the disease.
breast carcinoma (continued). "Similar to SALL2, SALL1 is downregulated in human breast cancer cells and tissues and correlates with ESR1 expression." (PMID 34944911, 2021). "(A) SALL1 expression in tumor cells in breast cancer and melanoma tissues was determined using the immunohistochemical staining." (PMID 29625565, 2018). "Improved understanding of these molecular processes mediated by SALL1 for the regulation of tumor biology and tumorigenesis will open new avenues to develop novel therapeutic strategies in human breast cancer and possibly other tumors." (PMID 29625565, 2018). "Specifically, we observed that SALL1 gene expression in breast cancer strongly suppresses tumor growth and proliferation, as well as induces cell cycle S phase arrest, which is mechanistically independent of apoptosis or cytolysis." (PMID 29625565, 2018). "In this study, we were the first to show that SALL1 also plays a critical role in control of genome stability, cell-cycle progression and cell fate in breast cancer." (PMID 29625565, 2018). "To further identify potential mechanism responsible for the down-regulation of SALL1 in breast cancer, we explored promoter methylation status of the SALL1 gene via COSMIC genome browser." (PMID 29625565, 2018). "In parallel, we studied the cell cycle distribution of the breast cancer cells transfected with SALL1." (PMID 29625565, 2018). "A recent report identified SALL1 as a tumor suppressor in human breast cancer, using an in vivo RNAi screen strategy." (PMID 29625565, 2018). "We first determined SALL1 gene expression levels in breast cancer cell lines using Real-time PCR analyses." (PMID 29625565, 2018). "SALL1 expression in human and murine breast cancer cells inhibited cancer cell growth and proliferation, metastasis, and promoted cell cycle arrest." (PMID 29625565, 2018). "(B) SALL1 expression in breast cancer cells induced expression of phosphorylated active of ATM in the transfected cells." (PMID 29625565, 2018). "Using loss-of-function strategies, we demonstrated that the mTOR inhibitor rapamycin and shRNA to specifically knock down mTOR gene expression in breast cancer cells dramatically prevented induction of senescence in tumor cells mediated by SALL1 expression." (PMID 29625565, 2018). "We selected two probes that indicate a methylation difference of the SALL1 promoter in COSMIC between the primary tumor in breast cancer and solid normal tissues." (PMID 29625565, 2018). "Collectively, these studies suggest that SALL1 functions as a tumor suppressor in breast cancer and directly controls cancer cell fate and metastasis." (PMID 29625565, 2018). "(B) Over-expression of SALL1 in E0771 breast cancer cells markedly suppressed the tumor cell migration and metastasis in NSG mice." (PMID 29625565, 2018). "We further discovered that SALL1-mediated suppression of breast cancer cells is due to the induction of tumor cell senescence as shown by induction of SA-β-Gal." (PMID 29625565, 2018). "Future studies will continue to focus on the identification of the subunits of NuRD and target genes recruited by SALL1 in breast cancer cells responsible for the regulation of DNA-damage response and senescence induction." (PMID 29625565, 2018). "We found a substantial decrease of SALL1 expression in the basal like breast cancer compared with that in normal breast tissue (p < 0.001), which is consistent with the previous report." (PMID 29625565, 2018). "(C) SALL1 promoter genes are highly methylated in the primary breast cancer tissues comparison with solid normal tissues." (PMID 29625565, 2018). "In the current study, we showed that SALL1 expression was significantly down-regulated in specific human breast cancer subtypes based on analyses of clinical tumor samples and cell lines." (PMID 29625565, 2018).
breast carcinoma (continued). "We further demonstrated that SALL1 expression in human and murine breast cancer cells controlled tumor cell growth and proliferation in vitro, and that overexpression of SALL1 inhibited tumorigenesis and metastasis in vivo in breast cancer xenograft models." (PMID 29625565, 2018). "Using both in vitro co-culture system and in vivo breast tumor models, we investigated how SALL1 expression in breast cancer cells affects tumor cell growth and proliferation, metastasis, and cell fate." (PMID 29625565, 2018). "In contrast, SALL1 gene expression levels in all the tumor cell lines from breast cancer, prostate cancer, colon cancer and lymphoma were significantly down-regulated." (PMID 29625565, 2018). "To better understand the role of SALL1 in the pathogenesis of breast cancer, we investigated the mechanism of SALL1 tumor suppressor activity in breast cancer models." (PMID 29625565, 2018). "Collectively, these results clearly indicate that SALL1 recruits NuRD in breast cancer cells resulting in suppression of tumor growth and proliferation, and induction of tumor cell senescence." (PMID 29625565, 2018). "Our studies indicate that the developmental control gene SALL1 plays a critical role in tumor suppression by recruiting the NuRD complex and thereby inducing cell senescence in breast cancer cells." (PMID 29625565, 2018). "We further demonstrated that the mechanism of inhibition of breast cancer cell growth and invasion by SALL1-NuRD depends on the p38 MAPK, ERK1/2, and mTOR signaling pathways." (PMID 29625565, 2018). "Treatment of MCF-7, MDA and E0771 breast cancer cells with KU55933 dramatically suppressed the phosphorylation of ATM in SALL1-transfected tumor cells and prevented induction of senescence in tumor cells." (PMID 29625565, 2018). "We first determined the activation and phosphorylation of MAPKs, including ERK1/2, p38 and JNK in breast cancer cells transfected with SALL1 using western blot analyses." (PMID 29625565, 2018). "(A) Over-expression of SALL1 in MCF-7 breast cancer cells significantly inhibited the migration of tumor cells compared with the control mSALL1 and vector-transfected tumor cells in the wound closure assays." (PMID 29625565, 2018). "We analyzed SALL1 expression levels in human and murine breast cancer cells as well as cancer tissues from different types of breast cancer patients." (PMID 29625565, 2018). "Numbers of SALL1+ tumor cells in melanoma tissues were much higher than those in breast cancer tissues." (PMID 29625565, 2018). "Our studies clearly demonstrate that SALL1 is a tumor suppressor in breast cancer and plays a critical role in directing tumorigenesis and metastasis." (PMID 29625565, 2018). "To further investigate the SALL1 expression in human breast cancer, we determined the SALL1+ cell numbers in cancer tissues from breast and melanoma cancer patients, using immunohistochemical staining analyses." (PMID 29625565, 2018). "Consistent with the gene expression results, we found that melanoma tumor tissues contained larger numbers of SALL1+ cells (mean 232/field), while in breast cancer tissues, the SALL1+ cells were low (mean 50/field)." (PMID 29625565, 2018). "In breast cancer, SALL1 acts as a tumor suppressor that recruits the NuRD complex and thereby induces cell senescence." (PMID 30237858, 2018). "The analysis revealed that there was significantly lower expression of SALL1 in the ER− breast cancer than that in the ER+ cancer tissues and normal breast tissues (p = 0.006 and p = 0.008, respectively)." (PMID 29625565, 2018). "Knockdown of SALL1 in breast cancer cells promoted cancer cell growth, proliferation, and colony formation." (PMID 29625565, 2018). "Our current studies further identified important roles of these two signaling pathways in SALL1-mediated regulation in breast cancer cells." (PMID 29625565, 2018).
breast carcinoma (continued). "SALL1 (Spalt-Like Transcription Factor 1), a zinc-finger transcription factor, was reported to function as a tumor suppressor in several cancers, including breast cancer and glioma, and accumulating evidence support its involvement in tumor biology." (PMID 42122151, 2026). "In addition to SALL4 and SALL2, studies in breast cancer lines showed that SALL1 inhibition increases cell migration and correlates with decreased cadherin 1 expression." (PMID 36438565, 2022). "Five-azacitidine also restored SALL1 expression on methylated breast cancer cell lines." (PMID 34944911, 2021). "SALL1 acted as a tumor suppressor gene in human glioma and breast cancer." (PMID 34257535, 2021). "The restoration of SALL2 and SALL1 expression with DNMTi may directly impact breast cancer treatment, increasing tamoxifen sensitivity in tamoxifen-resistant breast cancers." (PMID 34944911, 2021). "SALL1, SALL2, and SALL3 hypermethylation are associated with bad prognosis in several cancers, and the epigenetic silencing of SALL2 confers tamoxifen resistance in breast cancer." (PMID 34944911, 2021). "However, in contrast to the AML context, SALL1 over-expression in MDA breast cancer cells inhibited tumor cell growth and proliferation." (PMID 34944911, 2021). "We demonstrated that SALL1 functions as a tumor suppressor in breast cancer, which is significantly down-regulated in the basal like breast cancer and in estrogen receptor (ER), progesterone receptor (PR) and epidermal growth factor receptor 2 (HER2) triple negative breast cancer patients." (PMID 29625565, 2018). "We first performed xenograft models to investigate whether over-expression of SALL1 in breast cancer cells can affect tumor growth and development." (PMID 29625565, 2018). "Furthermore, we also compared SALL1 expression in breast cancer patients with different hormone receptors, estrogen receptor (ER) and Progesterone receptor (PR), or HER2 expression statuses." (PMID 29625565, 2018). "We identified SALL1 as a novel tumor suppressor in breast cancer." (PMID 29625565, 2018). "Given that ER, PR and HER2 expression levels in tumor cells are important prognostic factors for breast cancer outcomes, we also determined whether SALL1 had different expression in breast cancer patients with different ER, PR or HER2 expression statuses." (PMID 29625565, 2018). "We therefore reasoned that induction of senescence might be the mechanism involved in the suppressed cell growth and proliferation mediated by SALL1 overexpression in breast cancer cells." (PMID 29625565, 2018). "We investigated whether SALL1 could function as a tumor suppressor and dissected the molecular mechanism by which it regulates human breast cancer." (PMID 29625565, 2018). "Given the recent study identifying that SALL1 could be a tumor suppressor in human breast cancer, it is important to determine how SALL1 regulates breast cancer cell biology and functions." (PMID 29625565, 2018). "Similarly the SALL1 expression was lower in PR− breast cancer than that in PR+ breast cancer or the normal breast tissues (p < 0.001 and p = 0.0059, respectively)." (PMID 29625565, 2018). "Consistent with the previous report showing that the SALL1 promoter was methylated in breast and other epithelial cancers, our analysis also demonstrated that the genes were highly methylated in the 2 regions of the SALL1 promoter in the breast cancer tissues." (PMID 29625565, 2018). "In addition, our complementary in vivo studies demonstrated that SALL1 expression and NuRD recruitment in breast tumor cells inhibited tumorigenesis and metastasis in breast cancer models in vivo." (PMID 29625565, 2018). "Our studies clearly indicate that SALL1 functions as a tumor suppressor in breast cancer, which could be a novel target for human breast cancer therapy." (PMID 29625565, 2018).
breast carcinoma (continued). "We therefore hypothesized that SALL1-mediated suppression of breast cancer growth and proliferation, and induction of tumor cell senescence may also act through the recruitment of the NuRD complex." (PMID 29625565, 2018). "A recent paper demonstrated that SALL1 could be a tumor suppressor in human breast cancer, using an in vivo RNAi screen strategy." (PMID 29625565, 2018). "We thus determined whether SALL1 could alter the expression of other members in the SALL family mediating breast cancer growth suppression." (PMID 29625565, 2018). "Furthermore, our studies indicate that SALL1 expression in breast cancer selectively utilizes both MAPK and mTOR signaling pathways controlling tumor cell fate and functions." (PMID 29625565, 2018). "We therefore explored whether SALL1-induced breast cancer cell cycle S phase arrest and conversion of cancer cells into senescent cells involved MAPK signaling modulation." (PMID 29625565, 2018). "We observed that the genes were highly methylated in these 2 regions of SALL1 promoter in the breast cancer tissues, which might be partially responsible for the down-regulation of SALL1 in breast cancer." (PMID 29625565, 2018). "Besides the recruitment of NuRD complex, our current study also identified senescence induction as a novel mechanism mediated by SALL1 for the regulation of tumor biology and tumorigenesis in breast cancer." (PMID 29625565, 2018). "We next investigated whether mTOR signaling is also involved in the SALL1-induced breast cancer growth inhibition and senescence induction." (PMID 29625565, 2018). "Additionally, SALL1 has been reported to suppress breast cancer progression." (PMID 40647501, 2025). "SALL1 phosphorylation by PKC may also be involved in breast cancer." (PMID 34944911, 2021). "Spalt like transcription factor 1 (SALL1) encodes a zinc finger transcriptional repressor, which has recently been identified as a tumor suppressor gene, whose expression was in positive correlation with CDH1 and associated with the survival of patients in breast cancer." (PMID 30233644, 2018). "Importantly, we also provide evidence demonstrating that the SALL1-mediated suppression of tumor growth, cell proliferation and induction of tumor cell senescence depends on the endogenous recruitment of NuRD complex in breast cancer cells." (PMID 29625565, 2018). "In addition, whether SALL1 recruits the NuRD complex to perform its tumor suppressor function in breast cancer is unclear." (PMID 29625565, 2018). "Notably, analyses of TCGA normalized log2 transformed breast cancer argilent microarray expression data sets clearly showed a significant decrease of SALL1 gene expression in the basal like breast cancer, as well as in ER−, PR− and triple negative breast cancer tissues." (PMID 29625565, 2018). "However, transfection of the mutated SALL1 in the breast cancer cells did not have any effects on cell senescence and cell cycle, similar to that of control vector, suggesting that breast cancer cell senescence mediated by SALL1 depends on NuRD recruitment." (PMID 29625565, 2018). "In addition, given the multiple functions mediated by different subunits of the NuRD complex, identification of the precise assembly of NuRD components recruited by SALL1 in breast cancer cells will facilitate our understanding the functional role of SALL1 gene in tumor biology." (PMID 29625565, 2018). "Several independent studies suggest that SALL1, SALL2, and SALL4 play a role in the origin, progression, and response to breast cancer therapy." (PMID 34944911, 2021). "Moreover, an instance where SALL1 influences gene operation is already known: its role as a tumor suppressor in breast cancer, which is downregulated in estrogen receptor, progesterone receptor, and epidermal growth factor receptor-2 “triple negative” breast cancer patients." (PMID 35707773, 2021).
breast carcinoma (continued). "For instance, associated with their tumor suppressor role, the hypermethylation of the SALL1 and SALL2 promoters were described in breast cancer and esophageal squamous cell carcinoma (ESCC)." (PMID 34944911, 2021). "To confirm the physical interaction of SALL1 with the NuRD complex in cancer cells, we transfected MCF-7 breast cancer cells with GST fusions of wild type SALL1, or SALL1-S2A and SALL1-S2E." (PMID 29625565, 2018). "Collectively, our results suggest that SALL1 expression is significantly down-regulated in human breast cancer cells and in certain types of breast cancer tissues (especially in triple negative breast cancer), which may play a critical role in the pathogenesis of human breast cancer." (PMID 29625565, 2018). "We observed that transfection with SALL1 significantly increased the gene expressions of Cyclin A2, Cyclin B1, Cyclin E1, CDK2 and CDK4 in breast cancer MDA cells, which are important for checkpoint regulation in G1-S transition and S phases." (PMID 29625565, 2018). "However, whether and how SALL1 regulates human breast cancer is still unclear." (PMID 29625565, 2018). "We will continue our efforts to identify the molecular interactions and regulatory mechanisms between SALL1, NuRD, and ER, PR and HER2, in the regulation of tumorigenesis and metastasis in breast cancer." (PMID 29625565, 2018). "However, we did not identify any mutations that could account for SALL1 down-regulation in breast cancer." (PMID 29625565, 2018). "As we expected, transfection of SALL1-S2E into MCF-7 and E0771 breast cancer cells lost the ability to induce tumor cell senescence." (PMID 29625565, 2018). "In summary we have identified 5 (EMILIN2, SALL1, DBC1, FBLN2, CIDE-A) genes that demonstrated frequent tumour acquired methylation in breast cancer." (PMID 20205715, 2010). "Both measures with high ranks indicated 5 SNPs (SALL1 rs10521222; HLA-DQA1 rs9271608; DUSP1 rs17658229; APOC1 rs4420638; and TRAIP rs2352975) and 3 lifestyles (duration of OC and E + P use and BMI) as the most influential variables for breast cancer." (PMID 33441805, 2021). "Similarly, SALL1 knockdown led to the differential expression of EMT markers, such as E-cadherin and vimentin in SUM149 breast cancer cells, leading to increased cell migration in vitro." (PMID 34944911, 2021). "SALL1, SALL2, and ESR1 expression analyses could help to categorize breast cancer patients who may benefit from combined therapies: tamoxifen and DNMTi." (PMID 34944911, 2021). "Two SNPs (SALL1 rs10521222 and HLA-DQA1 rs9271608) and lifestyles, including alcohol intake, lifetime cumulative exposure to estrogen, and overall and visceral obesity, are the most common and strongest predictive markers for breast cancer across the analyses." (PMID 33441805, 2021). "Besides MYC itself, we find upregulation of other breast cancer stem cell factors (SOX2, SOX18, THY1, EYA1, GLI2, SALL1, GLIS1, CXCR4), suggesting that MYC HME cells adopt a stem-like state." (PMID 31942031, 2020). "In contrast to SALL1 gene expression, we found significantly higher expression of SALL4 in both breast cancer cell lines and primary cancer tissues, suggesting that SALL1 and SALL4 may have distinct functional roles in the regulation of breast cancer." (PMID 29625565, 2018). "As expected, silencing of SALL1 expression in MCF-7, MDA-MB-231 and E0771 breast cancer cells dramatically promoted tumor growth and increased cell proliferation compared with lentivirus carrying control shRNA infected breast cancer cells." (PMID 29625565, 2018). "We found that transfection of SALL1 but not mutated SALL1 selectively activated ERK1/2 and p38, but not JNK, resulting in significantly enhanced phosphorylation of ERK1/2 and p38 in both MCF-7 and E0771 breast cancer cells." (PMID 29625565, 2018). "However, no changes in PTEN expression were detected in breast cancer cells with SALL1 over-expression, suggesting that the regulation of PTEN by SALL1 is tissue-specific." (PMID 34944911, 2021).